IL5 (interleukin 5)
Diseases named in the same sentence as IL5 in open-access papers (continued):
Sharing a sentence is not in itself a finding about the gene and the disease.
tuberculosis (13 papers, 2012 to 2025). A chronic, recurrent infection caused by the bacterium Mycobacterium tuberculosis. "The panel we employed included cytokines that are elevated in tuberculosis, i.e., interferon gamma (IFNγ), IL-2, IL-5, IL-10, IL-17, GM-CSF and TNFα." (PMID 38415011, 2024). "Raised IL-5 levels were found in diseased BALs compared to healthy but this increase reached statistical significance in tuberculosis only." (PMID 22815689, 2012). "The best fit model found was log(P(Tuberculosis)/P(sarcoidosis)) = 1.214 + 8.884 * IL1 + 0.075 * IFN + 0.32 * IL12p70 + 0.039 * TNF − 0.097 * IL5 − 0.015 * IL8 − 0.73 * IL13 − 0.606 * IL10 − 2.404 * IL2 − 4.231 * IL4." (PMID 22815689, 2012). "IL10 and IL-5 levels were lower in latently infected individuals than tuberculosis patients." (PMID 32962082, 2020). "This cytokine that has been reported to be increased in those patients with DM2 and tuberculosis, common comorbidity associated with immunodeficiency in DM2 patients; nevertheless, further investigation is needed to confirm the role of IL-5 in susceptibility to infections in DM2." (PMID 31915708, 2019). "Fractalkine, IL-17, IL-6, IL-9, MIP-1β, CRP, VEGF, and IL-5 levels in saliva and IL-6, IL-2, SAP, and SAA levels in serum were significantly higher in tuberculosis patients (P < 0.05)." (PMID 24327799, 2013). "Tuberculosis triggers a type 1 immune response characterized by IL-12, IFN-γ, and TNF-α production, while toxocariasis elicits a type 2 response, mediated by cytokines such as IL-4, IL-5, IL-13, and IL-33." (PMID 40943043, 2025). "The CD patients with MAP infection in the TU/ACU study had elevated (IFNγ), TNFα and IL-17A like tuberculosis patients, but they did not have elevated IL-2, IL-5, IL-10 and GM-CSF typically reported in tuberculosis patients." (PMID 38415011, 2024). "Our data showed that mycobacterium tuberculosis (Mtb)-specific IFN-γ, TNF-α, IL-2, IL-6, IL-10, IL-5, IP-10, IL-1Ra, CXCL-1 and MCP-1 responses based on QFT-Plus significantly differed between Mtb-infected (including ATB, LTBI and previous TB) and uninfected healthy populations." (PMID 38166667, 2024). "However, in contrast to tuberculosis patients, the CD patients in the TU/ACU study did not have statistically significant increased IL-2, IL-5, IL-10, and GM-CSF." (PMID 38415011, 2024).
Anxiety (12 papers, 2018 to 2025). Intense feelings of nervousness, tension, or panic often arise in response to interpersonal stresses. "IL-5-treated mice exhibited similar general behavior and anxiety as PBS-treated mice at 5 weeks post-treatment." (PMID 34229727, 2021). "However, in the current study, mice that showed low-calling rates demonstrated higher levels of lung IL-5 gene expression, more anxiety-related behavior, longer latencies to approach novelty and increased hippocampal GR gene expression." (PMID 30214402, 2018). "The results from the open field and elevated plus maze tests indicate that IL-5 treatment did not significantly affect the general locomotor or anxiety levels of 3xTg-AD mice." (PMID 34229727, 2021).
bronchiectasis (12 papers, 2017 to 2025). Segmental, irreversible dilation of the bronchial tree resulting in the accumulation of secretions which leads to obstruction. "Two real-world studies indicated that IL-5 antagonists were effective in reducing oral corticosteroids and improving respiratory function in patients with coexistent bronchiectasis and severe eosinophilic asthma." (PMID 37653511, 2023). "Five bronchiectasis patients with a concomitant diagnosis of severe eosinophilic asthma were treated with anti-IL5 and anti-IL5-ra (i.e., two with benralizumab and three with mepolizumab)." (PMID 34356836, 2021). "Finally, anti-IL5 or anti-IL5ra drugs result in successful outcomes in severe eosinophilic asthmatic patients with concomitant bronchiectasis." (PMID 34356836, 2021). "Furthermore, our results suggest the effective role of anti-IL5 and anti-IL5-ra in bronchiectasis patients, with a 2-year follow-up." (PMID 34356836, 2021). "Moreover, in our center we have already observed that targeting IL-5 in severe eosinophilic asthma with bronchiectasis may be a good therapeutic strategy." (PMID 40142883, 2025). "Monoclonal antibodies (e.g., mepolizumab and benralizumab, which block IL-5 and IL-5 receptor -IL5ra-, respectively) can reduce the exacerbation rate and improve the quality of life and are able to spare systemic corticosteroid in eosinophilic severe asthmatic patients with bronchiectasis." (PMID 34356836, 2021). "In recent years, novel biomarkers, such as those related to IL-5, IL-33 and COL4A3 are emerging, but their expressions and potential roles in bronchiectasis still await investigation." (PMID 37653511, 2023). "Similarly to EGPA, biologics targeting IL5/IL5r have shown to improve exacerbation frequency and OCS consumption in patient with SEA and bronchiectasis." (PMID 38327518, 2024).
multiple sclerosis (12 papers, 2010 to 2025). A progressive autoimmune disorder affecting the central nervous system resulting in demyelination. "IL-5 enhances the production of B1 cells which are anti-inflammatory (impaired B1 cells have been found in multiple sclerosis, systemic lupus erythematosus, and rheumatoid arthritis), and IL-13 has anti-inflammatory properties." (PMID 40284540, 2025). "Our results showed that patients diagnosed with de novo multiple sclerosis had lower levels of IL-5 in CSF than in the healthy population." (PMID 39000506, 2024). "Glatiramer acetate administration increased serum IL-5/IL-13 levels in healthy subjects, untreated multiple sclerosis patients, and those with other neurological diseases, correlating with clinical efficacy." (PMID 38612591, 2024). "In a rat model of multiple sclerosis, IL-5 administration had therapeutic effects, acting at least in part by inducing FoxP3+ regulatory T cells." (PMID 23940537, 2013). "Ongoing studies on the effects of glatiramer acetate (GA, Copaxon, formerly Copoly-mer-1) on IL-5 and IL-13 production in patients with multiple sclerosis have shown that those with a positive clinical response to treatment had elevated serum IL-5 and IL-13 levels." (PMID 39000506, 2024). "Additional soluble factors secreted from NK2 cells are likely to be involved in this regulation, but the NK cells from iBD patients did not express IL-5, which plays a primary role in Th1 inhibition in multiple sclerosis patients in remission." (PMID 20459787, 2010).
vasculitis (12 papers, 2021 to 2026). "In the investigated model, lymphocyte infiltration in lung tissue and cytokines other than or in addition to IL-5 were suggested to have contributed to the development of vasculitis." (PMID 40176907, 2025). "Our case supports information on this rare manifestation which has been described in a previous case series, and demonstrates the good prognosis of this form of vasculitis when treated with corticosteroids and interleukin-5 inhibitors." (PMID 37116063, 2023). "Currently the only approved anti-IL-5 agent for eosinophilic granuloma and vasculitis." (PMID 40732309, 2025). "Therefore, it is crucial to further promote the accumulation and analysis of cases of vasculitis relapse in patients undergoing anti-IL-5 therapy." (PMID 39416779, 2024). "Furthermore, in recent years, several cases have been reported where patients undergoing anti-IL-5 therapy targeting T2-eosinophilic inflammation experienced a relapse of vasculitis in EGPA, marked by an increase in ANCA levels, despite having normal eosinophil counts." (PMID 39416779, 2024). "To test the role of ILC2s in vasculitis, we crossed IL5Tg mice to Il5Red5CreROSA-DTA ILC2-deficient R5/R5 deleter (ILC2del) mice, in which mature ILC2s — which constitutively produce IL-5 — are deleted via Cre-inducible expression of diphtheria toxin alpha from the endogenous IL-5 promoter." (PMID 33974563, 2021). "The results showed that the anti-IL-5 antibody did not sufficiently suppress the development of vasculitis in this model." (PMID 40176907, 2025). "The non-clinical data from the present study indicate that IL-5 signaling is not primarily involved in the development of vasculitis in the OVA-induced eosinophilic vasculitis mouse model." (PMID 40176907, 2025). "The detection of vasculitis from extra-respiratory organs and of p-ANCA in the blood are of great importance for the initiation of timely immunosuppressive therapy using cyclophosphamide, cortisone, or anti-IL-5(R) antibodies." (PMID 38549809, 2024). "Even during IL-33 administration, ILC2s were the predominant population of IL-5–expressing cells in the mouse lung, indicating that deletion of Th2 cells was unlikely to explain the absence of vasculitis." (PMID 33974563, 2021). "Alternatively, therapy with anti-interleukin-5 monoclonal antibodies (mepolizumab, benralizumab) or rituximab (monoclonal antibodies against CD20-positive B lymphocytes), which should preferably be carried out by vasculitis centers experienced in the treatment of EGPA." (PMID 38549809, 2024).
Airway obstruction (11 papers, 2015 to 2025). Obstruction of conducting airways of the lung. "However, cytokine distribution varied according to pulmonary function: IL‐17 (p = 0.001) and IL‐5 (p = 0.045) were associated with the presence of airway obstruction, and IL‐17 also differed according to bronchodilator response in FEV1 (p = 0.041)." (PMID 41159221, 2025). "IL‐17 (p = 0.001) and IL‐5 (p = 0.045) levels varied with airway obstruction, and IL‐17 levels differed with bronchodilator response in FEV1 (p = 0.041)." (PMID 41159221, 2025). "Th2 cells generate the proinflammatory cytokines IL-4, IL-5, and IL-13, which trigger mast cell and basophil activation, leading to inflammation and airway obstruction." (PMID 39421735, 2024). "Interleukin 5 (IL-5) and 13 (IL-13) regulate airway obstruction, hyperreactivity, and remodeling." (PMID 30542075, 2018). "Therefore, reslizumab may preferentially reverse airway obstruction which appears ‘fixed’ to β2-agonists (albuterol) due to action on IL-5 and airway eosinophils." (PMID 32328116, 2020).
myocardial infarction (11 papers, 2011 to 2026). Gross necrosis of the myocardium, as a result of interruption of the blood supply to the area, as in coronary thrombosis. "Previous studies have found that IL‐5 can regulate cardiac remodelling, such as improving cardiac remodelling after myocardial infarction and exacerbating cardiac remodelling induced by hypereosinophilia." (PMID 38963241, 2024). "When a targeted depletion of eosinophils in mice with myocardial infarction is conducted, it can reduce the positive impact of IL-5." (PMID 38879568, 2024). "IL-5 can facilitate the recovery of cardiac dysfunction post-myocardial infarction by promoting eosinophil accumulation and subsequent macrophage polarization." (PMID 37686855, 2023). "Furthermore, in a mouse model of myocardial infarction, TNF-α mRNA, IL-1α, IL-2, IL-4, IL-5, IL-6, IL-10, IL-17A, TNF-α, IFN-γ, and GM-CSF expression were all lower in the infarct area of TLR4-deficient mice compared with wild-type mice." (PMID 30399158, 2018). "It has been reported that IL-5 cardiac protein levels increase four days after Myocardial Infarction (MI) in a mouse model; on the contrary, as yet no data is available on IL-5 serum or plasma levels in chronic heart failure patients." (PMID 21418620, 2011).
rheumatoid arthritis (11 papers, 2015 to 2025). A chronic, systemic autoimmune disorder characterized by inflammation in the synovial membranes and articular surfaces. "In rheumatoid arthritis, the involvement of eosinophils has been linked to IL-5 and TGF-β1, profibrogenic cytokines that contribute to collagen accumulation in tissues." (PMID 26693492, 2015). "However, a second steroid-sparing agent should be considered, especially in this patient with concomitant rheumatoid arthritis, such as mepolizumab, an anti-IL-5 agent, along with a disease-modifying agent to control symptoms related to the previously known articular inflammatory disease." (PMID 39881915, 2024). "There was profound increment of interleukin 4 (IL-4), IL-5, and clusterin (P < 0.001) in the salivary proteome of 48 patients with pSS, compared to controls without pSS including 12 patients with rheumatoid arthritis (RA) and 12 healthy individuals." (PMID 26362815, 2015).
eczema (10 papers, 2010 to 2024). "Research reports examining cytokines in the skin of patients with ICI-induced cutaneous symptoms have found increased production of Th2 cytokines such as IL-4, IL-5, and IL-13 in cases of urticaria, pruritus, and eczema." (PMID 39200350, 2024). "Monoclonal antibodies targeting allergic immune effectors, including omalizumab (IgE), dupilumab (IL-4 and IL-13), reslizumab, benralizumab, and mepolizumab (IL-5), have shown efficacy in treating the eczema and other allergic manifestations." (PMID 37727514, 2023). "The pathogenesis in eczema is complex, and many different cytokines are involved, such as IL-4, IL-5, IL-13, and IL-17." (PMID 33815560, 2021). "HDM-specific IL-5 and IFN-γ responses at age 3 years were independently and positively associated with the presence of eczema at age 8 years." (PMID 24875149, 2014). "Scratching but not doctors diagnosed eczema was associated with higher levels of maternal IL-5, IL-6, and IL-13 during pregnancy." (PMID 27222655, 2016). "We report that scratching behavior but not doctors diagnosed eczema among infants was associated with higher levels of maternal serum but not breast milk IL-5, IL-6, and IL-13 cytokines." (PMID 27222655, 2016).
endometriosis (10 papers, 2017 to 2024). The growth of functional endometrial tissue in anatomic sites outside the uterine body. "Several serum cytokines such as interleukins (IL) IL1β, IL-5, IL-6, IL-7 and IL-12 are involved, and their levels were found to be altered in endometriosis as compared to in healthy women." (PMID 39309679, 2024). "Studies suggest endometriosis as a contributing factor in ovarian cancer, with cytokines IL-2, IL-5, IL-6, IL-8, and IL-10 detected in serum, intra-cystic fluid, and peritoneal fluid in endometriomas and ovarian cancer patient samples." (PMID 39596309, 2024). "IL-5 is a hematopoietic growth factor with anti-inflammatory properties that negatively correlates with endometriosis." (PMID 39000283, 2024). "For instance, we detected a significant upregulation of IL-5, which is characteristic for the presence of early stage endometriosis and generally contributes to the proliferation, differentiation and survival of different cell types." (PMID 37762161, 2023). "Table III shows the AUC, sensitivity, and specificity of IL-3, IL-5, and IL-6 for diagnosis of endometriosis with confidence intervals." (PMID 35571503, 2021). "In this study, IL-3, IL-5, and IL-6 were measured in the FF of women with endometriosis." (PMID 35571503, 2021). "In inflammatory diseases, such as endometriosis, IL-5 is reduced as an anti-inflammatory factor." (PMID 35571503, 2021). "IL-3 and IL-6 were significantly changed in the FF of the women with endometriosis compared with the control group (p = 0.04, and p < 0.01, respectively), and the mean concentration of IL-5 in the endometriosis group was lower than in the control group (p = 0.5), but this was not significant." (PMID 35571503, 2021). "Furthermore, the mean concentration of IL-5 in the endometriosis group was lower than the control group (228.5 ± 180.7 ng/L vs. 195.8 ± 106.8 ng/L, p = 0.50)." (PMID 35571503, 2021). "It seems that IL-5 elicits local inflammation in women with endometriosis and may act at the earlier stages of this inflammatory condition to develop endometrial lesions." (PMID 35571503, 2021). "Along the same line, a lack of IL-5 also interfered with the menstrual cycle, dyspareunia, and dysmenorrhea in endometriosis." (PMID 39000283, 2024). "The present study demonstrated no significant reduction in the FF concentration of IL-5 between the endometriosis and control groups." (PMID 35571503, 2021). "While eosinophils have not been extensively studied in the context of endometriosis, eotaxin and IL-5 are elevated in the PF of patients with severe endometriosis." (PMID 34699382, 2021). "This study aims to investigate follicular fluid (FF) concentration of interleukin (IL)-3, IL-5, and IL-6 in women with and without endometriosis." (PMID 35571503, 2021). "Most of the previous studies have evaluated the concentration of interleukin-5 (IL-5) and IL-6 in the peritoneal fluid (PF) or serum of women with endometriosis and not in the follicular fluid (FF)." (PMID 35571503, 2021). "Although the FF concentration of IL-5 was reduced in endometriosis women, this change was not statistically significant." (PMID 35571503, 2021).
autism (9 papers, 2011 to 2022). Persistent deficits in social interaction and communication and interaction as well as a markedly restricted repertoire of activity and interest as well as repetitive patterns of behavior. "In addition, reports consistently delineate unchanged IL-13, IL-10, IL-5, and IL-4 levels in the plasma/serum and post-stimulated blood immune cells in individuals with autism as compared with controls." (PMID 36268027, 2022). "Notably, high levels of IL-5 in mid-gestation maternal serum samples were significantly associated with a 50% increased risk of ASD in the offspring, and especially of regressive autism." (PMID 23497090, 2013). "Results showed that, following toll-like receptor stimulation, the autism group with GIS had higher levels of cytokines including IL-5, IL-15, and IL-17 compared to the autism group that were not presenting with GIS." (PMID 32532137, 2020). "The Th1-Th2 paradigm, that is immune skewing toward type-1 cell-mediated immunity (interferon-gamma promoted immunity) vs. type-2 humoral immunity (IL-4, IL-5 and IL-13 promoted immunity), may not be properly applicable to immune alterations in autism." (PMID 21799730, 2011). "Therefore, our findings indicate that increased production of Th1 cytokines (IFN-γ) and Th17 cytokines (IL-17), along with no change in Th2 cytokines (IL-4, IL-5, and IL-13), might suggest a skewing toward the Th1/Th17 phenotype and dampening of the Th2 phenotype in the context of autism." (PMID 36268027, 2022).
Crohn disease (9 papers, 2012 to 2023). A gastrointestinal disorder characterized by chronic inflammation involving all layers of the intestinal wall, noncaseating granulomas affecting the intestinal wall and regional lymph nodes, and transmural fibrosis. "The gene-gene interaction network of the biomarker gene indicates the involvement of STAT3 and IL-5 genes linked to Crohn's disease's postoperative recurrence." (PMID 37994325, 2023). "The gene cluster on chromosome 5q31 harbors several immune related genes, including the interleukins IL3, IL5 and the interferon regulator IRF1, which have been associated with Crohn’s disease in the European population." (PMID 22606245, 2012).